OPN1LW (opsin 1, long wave sensitive)
Description:
G protein-coupled photoreceptor that selectively activates G(i) proteins in response to long-wavelength (red) light, thereby decreasing intracellular cAMP levels (PubMed:2937147, PubMed:6140680, Ref.5). Activation occurs when the opsin-bound cis-retinal chromophore absorbs a photon and isomerizes to all-trans-retinal, inducing a conformational change in the opsin that triggers a G protein-mediated phototransduction cascade (Ref.5). Mediates visual perception of red light in cone photoreceptor cells.
Synonyms: ROP; RCP; COD5; CBBM; CBP
Tractability: Small molecule: a structure with a bound ligand is known; it belongs to a druggable protein family. Antibody: its Gene Ontology location is reachable by antibodies, with high confidence; UniProt predicts a signal peptide or a membrane-spanning region.
Target class: Opsin; Membrane receptor; Family A G protein-coupled receptor
Gene: Protein-coding gene on chromosome X (154,144,243 to 154,159,032, forward strand). Ensembl gene ENSG00000102076.
Subcellular location: Membrane; Photoreceptor outer segment membrane
Pathways (Reactome):
Signal Transduction: G alpha (i) signalling events; Opsins
Disease: Defective visual phototransduction due to OPN1LW loss of function
Sensory Perception: The retinoid cycle in cones (daylight vision)
Gene Ontology:
Molecular function: G protein-coupled photoreceptor activity; photoreceptor activity; protein binding; G protein-coupled receptor activity
Biological process: absorption of visible light; positive regulation of cytokinesis; transducin-mediated opsin signaling pathway; visual perception; cellular response to light stimulus; G protein-coupled receptor signaling pathway; phototransduction; signal transduction
Cellular component: cone photoreceptor disc membrane; photoreceptor disc membrane; photoreceptor outer segment; plasma membrane; membrane
Gene-disease validity (ClinGen):
ClinGen rates the evidence that OPN1LW causes each of these diseases.
red color blindness (X-linked): Definitive. Protanopia is a severe type of color vision deficiency caused by the complete absence of red retinal photoreceptors.
Homologues: Orthologues: macaque OPN1LW (98% identical), macaque OPN1MW3 (96% identical), dog OPN1LW (89% identical), rabbit OPN1MW (88% identical), rat Opn1mw (87% identical), tropical clawed frog opn1lw (80% identical), guinea pig Opn1mw (79% identical), mouse Opn1mw (79% identical), zebrafish opn1lw1 (77% identical), zebrafish opn1lw2 (76% identical). Paralogues in human: OPN1MW (96% identical), OPN1MW2 (96% identical), OPN1MW3 (96% identical), RHO (42% identical), OPN1SW (41% identical), OPN3 (26% identical), OPN4 (24% identical), RRH (23% identical), OPN5 (20% identical).
Diseases named in the same sentence as OPN1LW in open-access papers:
OPN1LW is named in the same sentence as 16 diseases in open-access papers, as found by Europe PMC text mining. Sharing a sentence is not in itself a finding about the gene and the disease. The quoted sentences say what the papers report.
blue cone monochromacy (9 papers, 2015 to 2025). Blue cone monochromatism (BCM) is a recessive X-linked disease characterized by severely impaired color discrimination, low visual acuity, nystagmus, and photophobia, due to dysfunction of the red (L) and green (M) cone photoreceptors. "Blue-cone monochromacy (BCM) is an X-linked recessive disorder caused by pathogenic variants in the OPN1LW and OPN1MW genes." (PMID 40364109, 2025). "Blue cone monochromacy (BCM) is characterized by loss of function of both OPN1LW (the first) and OPN1MW (the downstream) genes on the X chromosome." (PMID 30065301, 2018). "Blue cone monochromacy (BCM) is a congenital retinal disorder caused by mutations in the OPN1LW / OPN1MW gene cluster on the X chromosome that controls the expression of the red (L, long wavelength) and green (M, middle wavelength) cone photoreceptor opsins." (PMID 25909963, 2015). "Blue cone monochromacy (BCM) is an X-linked retinal disorder caused by mutations in the OPN1LW/OPN1MW gene locus, resulting in impaired cone function and structural degeneration." (PMID 40297680, 2025). "Blue cone monochromacy (BCM) is a rare X‐linked disorder characterised by a marked reduction or absence of L‐opsin and M‐opsin expression (encoded by the neighbouring OPN1LW and OPN1MW genes), impairing L‐ and M‐cone function." (PMID 40013354, 2025). "Hemizygous variants of OPN1LW are also a well-established cause of blue cone monochromacy (BCM)." (PMID 41153400, 2025). "We used supervised machine learning to predict foveal function from foveal structure in blue cone monochromacy (BCM), an X-linked congenital cone photoreceptor dysfunction secondary to mutations in the OPN1LW/OPN1MW gene cluster." (PMID 32848570, 2020). "Blue cone monochromacy is characterized by attenuated or absent L-opsin and M-opsin expression encoded by OPN1LW and OPN1MW, and is strongly linked to high myopia." (PMID 40535564, 2025). "However, some genes have complex structures that are difficult to analyze, including the OPN1LW/OPN1MW gene cluster in blue cone monochromacy and the IKBKG/NEMO genes in incontinentia pigmenti." (PMID 39271608, 2024). "Among these IRDs is blue cone monochromacy (BCM), the X-linked congenital disorder with loss of red (L, long wavelength sensitive) and green (M, middle wavelength sensitive) cone photoreceptor function secondary to mutations in the OPN1LW/OPN1MW gene cluster on chromosome Xq28." (PMID 32848570, 2020).
myopia (2 papers, 2024 to 2025). "Surprisingly, genes associated with retinal disorders (CLUL1, VSX1, RD3, RS1, and CABP4) and a cone pigment (OPN1LW) were identified in choroid but not retina of progressing chick myopia." (PMID 39028695, 2024).
Dyschromatopsia (1 paper, 2022). A form of colorblindness in which only two of the three fundamental colors can be distinguished due to a lack of one of the retinal cone pigments. "Certain combinations of common variants in exon 3 of OPN1LW and OPN1MW, the genes encoding the apo-protein of the long- and middle-wavelength sensitive cone photoreceptor visual pigments in humans, induce splicing defects and have been associated with dyschromatopsia and cone dysfunction syndromes." (PMID 35743313, 2022).
male infertility (1 paper, 2023). The inability of the male to effect fertilization of an ovum after a specified period of unprotected intercourse. "Moreover, we investigate the Y-chromosome genes, DAZ1/DAZ2/DAZ3/DAZ4, of which structural variants have been linked to male infertility, and X-chromosome genes OPN1LW and OPN1MW linked to eye disorders." (PMID 37365340, 2023).
retinoblastoma (1 paper, 2022). A malignant tumor that originates in the nuclear layer of the retina. "Minigene splicing outcomes were similar in HEK293 cells and the human retinoblastoma cell line WERI-Rb1, the latter retaining a cone photoreceptor expression profile including endogenous OPN1LW and OPN1MW gene expression." (PMID 35743313, 2022).
Stickler syndrome (1 paper, 2024). Stickler syndrome is an inherited vitreoretinopathy characterized by the association of ocular signs with more or less complete forms of Pierre-Robin sequence, bone disorders, and sensorineural deafness (10% of cases). "Exome sequencing identified 21 potential pathogenic variants of 13 genes in 20 of 75 (26.7%) probands, including genes for Stickler syndrome (COL11A1 and COL2A1; 6/20), FEVR (FZD4, LRP5, and TSPAN12; 5/20), and others (FBN1, GPR179, ZEB2, PAX6, GPR143, OPN1LW, FRMD7, and CACNA1F; 9/20)." (PMID 38243264, 2024).
infectious disease (1 paper, 2023). A disorder directly resulting from the presence and activity of a microbial, viral, or parasitic agent in humans. "TSPY4, OPN1LW, CARF, CCDC14, HNRNPCL4, SSX2B genes need further exploration as it has not been identified in any infectious disease, including the recent COVID-19 pandemic." (PMID 37644081, 2023).
OPN1LW also shares sentences with these, for which no sentence is quoted: infection (2 papers); autosomal recessive cone rod dystrophy (1); cyst (1); diabetics (1); hearing loss (1); incontinentia pigmenti (1); Macular dystrophy (1); retinal disorder (1); type II diabetes (1).